INS (insulin)
Diseases named in the same sentence as INS in open-access papers (continued):
Sharing a sentence is not in itself a finding about the gene and the disease.
diabetes (continued). "However, the longer the duration of diabetes and the longer the insulin requirement, the higher the risk of their retinal changes." (PMID 34441264, 2021). "Diabetes mellitus includes a diverse group of metabolic diseases with the common feature of hyperglycaemia, which can be caused by insufficient insulin secretion and impaired insulin action on target tissues." (PMID 34299114, 2021). "In this nationwide population-based study including 37,965 patients with type 2 diabetes mellitus, we could show that over a study period of 6 years, insulin therapy was related to an increased risk of pneumonia in patients with type 2 diabetes mellitus." (PMID 34683125, 2021). "In the KEGG enrichment analysis, the hypo-DMRs genes were found to be mainly involved in insulin secretion, diabetes, dopaminergic synapse, and thyroid hormone signaling pathways, which may associate with the diabetes and hormonal disorders in PCOS patients." (PMID 34113617, 2021). "Also, information on diabetes management; i.e. follow-up routines on glycated haemoglobin (HbA1c), self-monitoring of blood glucose, insulin administration and risk factors (blood pressure, body mass index and nutritional status) were registered." (PMID 33691687, 2021). "Most cases may be categorised into one of two major categories, type 1, or type 2 diabetes (T2D), although more types of diabetes exist, including some caused by the genetic defects of both β-cell function and insulin action." (PMID 34299114, 2021). "In addition to reducing hepatic glucose production and increasing cell sensitivity to insulin, many studies have shown that metformin administration is beneficial in reducing vascular risk associated with diabetes." (PMID 34168187, 2021). "For instance, miRNAs such as let-7, miR-103, miR-29, miR-223 and miR-107 may be implicated in the pathogenesis of diabetes by mediating liver gluconeogenesis, insulin secretion and autophagy." (PMID 34959338, 2021). "Consequently, perturbation of insulin/IGF1 signaling (IIS) is usually associated with metabolic diseases like Diabetes mellitus and obesity." (PMID 33398091, 2021). "Several studies have reported that low magnesium intake is associated with type 2 diabetes mellitus (T2DM), and randomized controlled trials show that magnesium supplementation improves glucose parameters in adults with diabetes and improves insulin sensitivity in those at high risk of diabetes." (PMID 34836395, 2021). "Taken together, these data suggest that OCN efficiently improves glucose response in both insulin resistant and deficient mice and may possess a great potential to treat diabetes." (PMID 34489478, 2021). "A crosstalk between insulin and Igf-1 is mediated by the phosphorylation of Irs1 residues; thus, insulin/IGF-1 signaling could underlie the poor healing of injured muscles that is associated with diabetes." (PMID 33803124, 2021). "Other factors, including increased insulin sensitivity in muscle and adipocytes and protection of pancreatic β‐cells, might also be involved in the underlying mechanism of anti‐diabetes in LLKL." (PMID 33215869, 2021). "Diabetes mellitus (DM) describes a group of metabolic disorders and is mainly characterized by chronic hyperglycemia resulting from impaired insulin secretion or impaired insulin action or both mechanisms together, causing long-term complications." (PMID 34828808, 2021). "These study also indicated that the relatives had multiple factors predicting the development of diabetes mellitus, and that the spouses may share a number of common environmental factors associated with low insulin sensitivity." (PMID 34442147, 2021). "Medical treatment of diabetes, especially with insulin, and long duration of diabetes may exacerbate the risk of ischemic stroke and death compared to that experienced by a general population cohort." (PMID 33478504, 2021). "C-peptide adds value in the capture of those with rapidly progressive insulin deficient diabetes." (PMID 34803927, 2021).
diabetes (continued). "According to the American Diabetes Association guidelines, diabetic women taking oral hypoglycemic medication might be at risk of treatment failure and they should switch to insulin when they are pregnant." (PMID 34758755, 2021). "Diabetes mellitus (DM), also referred to as diabetes, is a chronic condition that results due to elevated levels of glucose in blood caused by the body ́s inability to produce any or enough of the hormone insulin or use insulin effectively." (PMID 34422158, 2021). "The disruption of normal insulin signaling owing to hyperinsulinemia, insulin resistance, or absolute insulin deficiency associated with diabetes causes dysregulation of FoxO1 phosphorylation and subcellular localization, leading to improper FoxO1 activity and its target genes transcription." (PMID 33859563, 2021). "Attenuation of hazard ratios after adjustment for triglycerides may be explained at least in part because of triglycerides being a marker of insulin sensitivity and a sensitive marker of future diabetes risk." (PMID 34555371, 2021). "The most common utilisation of TZD‐containing structures has been in the treatment of diabetes mellitus (DM), which is recognised as a metabolic disorder often characterised by hyperglycaemia and related ailments caused due to a deficiency in insulin secretion." (PMID 33844475, 2021). "Considering the associations documented between CD24 and cancer, we suggest that further investigation of the role of CD24 in insulin sensitivity and weight gain may elucidate associations between cancer and both diabetes and obesity." (PMID 33467499, 2021). "Four inactivating variants (p.R370S, p.E1506K, p.R1418H, and p.R1420H) have been demonstrated to decrease KATP channel activity and dysregulation of insulin secretion in functional studies, with the consequence that patients with these variants progressed to diabetes in later life." (PMID 34631896, 2021). "Approximately, 50% of people with PCOS develop diabetes or pre-diabetes before turning 40 years age; therefore, following a special lifestyle and diets that maintain body weight and eventually increases good insulin levels, reduces the risk of the disease and its associated adverse events." (PMID 34820542, 2021). "Diabetes is a chronic metabolic disease caused by insufficient insulin production and secretion and, in case of type 2 diabetes (T2D), the inability of tissues to adequately respond to insulin." (PMID 34205752, 2021). "Such compounds could represent exciting exploitable scaffolds for future drug discovery in diabetes, as well as providing tools to allow for a better understanding of cell signalling pathways linked to insulin secretion and metabolism." (PMID 34621137, 2021). "Diabetes mellitus is associated with high blood sugar levels for a long period of time due to alterations in carbohydrate, protein and fat metabolism, which results from a dysfunction in insulin secretion, insulin action, or both." (PMID 36699147, 2021). "However, metformin also increases insulin sensitivity and higher glucose and insulin levels are inversely associated with SU in adults with diabetes." (PMID 34444833, 2021). "The aim of this review is to provide a comprehensive and updated view of the most abundant circRNAs expressed in pancreatic islet cells, some of which originating from key genes controlling the differentiation and the activity of insulin-secreting cells or from diabetes susceptibility genes." (PMID 33546109, 2021). "Furthermore, upregulation of NPY receptor activation has also been linked to the improved insulin secretion and resolution of diabetes following bariatric surgery." (PMID 33716983, 2021). "Indeed, it is known that insulin levels rise almost a decade before diabetes is detected and are sometimes referred to as Stage 1 of diabetes associated with compensation." (PMID 34557366, 2021).
diabetes (continued). "Diabetes mellitus (DM) is a metabolic disease caused by the presence of high blood glucose levels or hyperglycemia resulting from impaired insulin secretion, defective insulin action, or both." (PMID 33802824, 2021). "Therefore, nutritional and lifestyle modifications aimed at reducing the insulin concentrations or insulin resistance can reduce the risk of developing diabetes." (PMID 33892738, 2021). "This review provides an overview of various patterns of intermittent fasting and shows the effect of intermittent fasting on human anthropometric such as excess body weight and biochemical parameters for example high glucose and fasting insulin, which are risk factors for diabetes." (PMID 33826120, 2021). "Death or dysfunction to insulin-secreting β-cells within the islet generally causes diabetes." (PMID 33939712, 2021). "Fluctuation in blood glucose level was also significantly associated with having at least one complication of diabetes (OR = 2.2, 95% CI = 1.2–3.9, p = 0.008) and reduced access to diabetes medicine was significantly higher in people who were on insulin (OR = 2.1, 95% CI = 1.3–3.3, p = 0.001)." (PMID 34715917, 2021). "Diabetes mellitus (DM) type 2 is a complex chronic metabolic disease, characterized by hyperglycemia, and produced by a deficiency or loss of insulin activity; DM is generally accompanied by alterations like dyslipidemia, hypertension, obesity, or hyperinsulinemia." (PMID 33670091, 2021). "In this way, as Unger supported for his whole life, glucagon could regulate glycaemia level but it could be much more, it could represent the real cause of diabetes, overcoming the role of insulin and its deficiency." (PMID 34572493, 2021). "In many cases, endothelial dysfunction associated with diabetes may result from an impaired response of this tissue to insulin; therefore, endothelium becomes one of the therapeutic targets in diabetes." (PMID 34426731, 2021). "Diabetes is a lifelong systemic disease induced by insulin secretion deficiency." (PMID 34098912, 2021). "However, the four OTUs associated with prevalent CVD did not overlap with those associated with related diagnostic and medication intake (diabetes, insulin and hypoglycemic drugs, CVD risk, and LDL-lowering drugs)." (PMID 34915914, 2021). "Additionally, in the case of diabetes, meta-analyses seem to confirm the important role of the bioelement in question not only for glucose parameters but also for increasing insulin-sensitivity parameters in people at high risk of diabetes." (PMID 33802529, 2021). "In addition to the PPI SP mutations, at least 70 INS gene mutations located in the proinsulin domain have been reported to be associated with diabetes in humans." (PMID 35069438, 2021). "Moreover, it is well known that a decrease in blood pressure and LDL levels is associated with better cardiovascular health, whereas a higher insulin sensitivity reduction decreases the risk of insulin resistance and diabetes." (PMID 33921979, 2021). "Indeed, impaired insulin secretion in response to glucose can be demonstrated in individuals at risk prior to the clinical onset of diabetes." (PMID 34843575, 2021). "The positive effects of albendazole on insulin and the short duration of treatment for diabetes may have caused partial changes in adiponectin level." (PMID 33641315, 2021). "Based on the existing evidence, the reduction in FABP4 levels may improve insulin sensitivity and lower diabetes risk." (PMID 34368366, 2021). "Furthermore, the association between the CD24 and insulin sensitivity suggests a possible mechanism for diabetes as a cancer risk factor." (PMID 33467499, 2021). "Another possible mechanism may be that ectopic liver fat is perhaps part of the pathogenic process in diabetes, resulting in hepatic insulin resistance, excess gluconeogenesis, and higher fasting glucose levels." (PMID 34992579, 2021).
diabetes (continued). "Collectively, postload hyperglycemia precedes to fasting hyperglycemia and diabetes, as results of a deficiency in insulin secretion and a decline in β-cell function, leading to consequent suppression of hepatic glucose production and decreases in peripheral glucose uptake." (PMID 35141297, 2021). "Taken together, this study suggested that AME could be helpful to prevent hepatic abnormality by regulation of insulin signaling associated with energy metabolism and autophagy in diabetes." (PMID 34679681, 2021). "One of the possible mechanisms is that individuals with stronger muscle strength have increased insulin action and lower blood sugar, which may help reduce the risk of diabetes." (PMID 34325672, 2021). "We also examined whether diabetes affected associations of the insulin measures with cerebrovascular pathology." (PMID 33858515, 2021). "Diabetes mellitus is a chronic disease caused by an impaired insulin secretion." (PMID 34443474, 2021). "For example, in our experiments, the relation of ‘diabetes’ with ‘cellulitis and abscess of legs’ in one visit is more prone to be a short-term complication, but the relation of ‘diabetes’ and ‘long-term use of insulin’ in two different visits is more prone to be causation." (PMID 34727940, 2021). "Allyl methyl sulfide (AMS), an active metabolite observed inside the body after oral administration of raw garlic, has been shown to effect diabetes by reducing glucose levels, increasing insulin levels, and reducing hepatic oxidative stress caused by glucotoxicity in diabetes." (PMID 35127948, 2021). "However, iron overload also resulted in decreased glucose tolerance and increased insulin secretory capacity, processes associated with obesity and diabetes." (PMID 34441564, 2021). "Deintensification of diabetes treatment regimens may include discontinuing drugs most likely to cause hypoglycemia (e.g. sulfonylureas, insulin) or switching to agents associated with a lower risk of hypoglycemia." (PMID 34911481, 2021). "Based on the 2020 Standards of Medical Care in Diabetes from the American Diabetes Association, T1D involves autoimmune β-cell destruction, whereas T2D is characterized by progressive loss of β-cell insulin secretion frequently on the background of insulin resistance." (PMID 33673206, 2021). "There is a possibility that the damage of pancreatic beta cells and increased insulin resistance, as well as impaired glucose metabolism, caused by COVID-19 may lead to the occurrence of diabetes in the future." (PMID 34299225, 2021). "High protein diets have been advocated by diabetes experts arguing for the diet’s lower energy density and higher satiating effect favoring weight loss, and lower endogenous and exogenous insulin needs which is thought to reduce insulin induced lipogenesis and improve blood lipid markers." (PMID 33805161, 2021). "Moreover, refined grains, white bread, and sugar-sweets desserts, which are constituents of the "western dietary pattern", rapidly increase the insulin and glucose levels in blood, which cause insulin resistance, diabetes, and obesity." (PMID 33509112, 2021). "A range of mechanisms may explain the link between increased levels of HDL-C and reduced risk of diabetes risk, including anti-inflammatory response mechanisms, improved insulin secretion and the uptake of glucose by the peripheral muscles." (PMID 34273996, 2021). "Moreover, gut microbiota-derived succinate levels are elevated in insulin-resistant obese individuals, indicating maladaptive microbiota–host crosstalk that promotes type 2 diabetes mellitus, cardiovascular disease, and associated inflammation." (PMID 34066026, 2021). "Additionally, many patients with Cushing’s disease or acromegaly have underlying impaired glucose tolerance or overt diabetes mellitus because of increased insulin resistance." (PMID 34275099, 2021).
diabetes (continued). "C5 could prevent the risk for diabetes mellitus by decreasing hepatic gluconeogenesis together with antioxidant, anti-inflammatory, and anti-insulin resistant actions mediated through AMPK/Akt." (PMID 33920678, 2021). "Over the past two decades, metabolomics has been widely utilized in large epidemiological studies, and some metabolites/pathways have been identified and validated to be associated with insulin metabolism or being predictive of diabetes across different studies." (PMID 34831057, 2021). "The biology of the insulin producing beta cells, including stimulation and secretion, has been extensively studied for years as the loss of beta cell function and insulin secretion is associated with diabetes." (PMID 33367617, 2021). "It has been shown that insulin could promote bone formation and prevent diabetes-induced bone loss by upregulating the serum osteogenesis factor, including osteoprotegerin (OPG) and osteocalcin (OC)." (PMID 33906655, 2021). "In addition, CD24 has been associated with diabetes, possibly through the associations between cancer, diabetes, and obesity, for which several molecular mechanisms have been proposed, including the insulin synthesis pathway and glucose regulation." (PMID 33467499, 2021). "Insulin plays an important role in glycaemic control, and deficient insulin actions may cause glucose intolerance and may progress to type 2 diabetes mellitus." (PMID 34844584, 2021). "However, some studies have shown that the higher acquisition costs of long-acting insulin analogues can potentially be offset by savings from averted costs of hypoglycaemia and other diabetes-associated complications." (PMID 34249838, 2021). "Since glucose homeostasis in diabetes can be disrupted not only by the loss of insulin-producing function and the development of β-cell dysfunction, but also by increasing the content of proinflammatory cytokines in the blood, a study of TNF-α content in experimental animals was conducted." (PMID 34572994, 2021). "Diabetes mellitus (DM), is a group of metabolic disorders that is characterized by a high blood glucose level (hyperglycemia), mainly caused by insufficient insulin production or unresponsiveness of the body to insulin or both." (PMID 34829618, 2021). "An increase in IR‐A could thus enhance IGF2‐mediated mitogenic signalling and decrease metabolic insulin signalling, which has been suggested as a cause of insulin resistance during the progression of diabetes." (PMID 33742502, 2021). "Diabetes can cause a rise in blood sugar and insulin levels and has an effect on inflammation that may contribute to depression." (PMID 34912246, 2021). "Diabetes causes oxidative stress, which further impairs insulin action." (PMID 34201848, 2021). "This could be consistent with the ability of the extract to restore an adequate insulin level, which prevents the metabolic changes associated with diabetes, lipogenesis and glycogenesis, and the breakdown of muscle proteins." (PMID 33572627, 2021). "Additionally, consumption of traditional Mexican food reduces the risk of pre-diabetes and lowers insulin levels, although effects on incident obesity are mixed." (PMID 34420524, 2021). "Interestingly, the MT2 variant is significantly associated with increased fasting blood glucose levels, reduced early insulin response to glucose, and increased risk of type 2 diabetes mellitus." (PMID 34439554, 2021). "The explanation may be that diabetes is generally more severe in insulin users than oral medicine users and the fracture risk cannot accurately reflect the influence of drugs on bone metabolism." (PMID 33906655, 2021). "On the other hand, insulin sensitivity and insulin secretion remained as significant independent predictors of dysglycemia, consistent with the prevailing notion that insulin resistance and deficient insulin secretion are key to the pathogenesis of diabetes." (PMID 34206745, 2021).